SNORD115-7 (small nucleolar RNA, C/D box 115-7)
Synonyms: HBII-52-7
Gene: Small nucleolar RNA gene on chromosome 15 (25,182,385 to 25,182,466, forward strand). Ensembl gene ENSG00000278089.
Gene Ontology:
Biological process: RNA processing
Cellular component: nucleolus
Homologues: Paralogues in human: SNORD115-11 (95% identical), SNORD115-29 (95% identical), SNORD115-36 (95% identical), SNORD115-43 (95% identical), SNORD115-12 (94% identical), SNORD115-16 (94% identical), SNORD115-22 (94% identical), SNORD115-26 (94% identical), SNORD115-39 (94% identical), SNORD115-44 (94% identical), SNORD115-6 (94% identical), SNORD115-9 (94% identical), and 37 more.